TRPV4 (transient receptor potential cation channel subfamily V member 4)
Diseases named in the same sentence as TRPV4 in open-access papers (continued):
Sharing a sentence is not in itself a finding about the gene and the disease.
channelopathies (12 papers, 2011 to 2025). "The phenotypes of all these TRPV4 mutations vary from severe neonatal lethality to mild impact, and thus our finding can be useful to understand the TRPV4‐mutation‐induced channelopathies better." (PMID 39648544, 2025). "Previous reports suggest that there are different point mutations that are located in the MTS region of TRPV4, and each of these point mutations is known to induce different channelopathies." (PMID 39648544, 2025). "Remarkably, over 80 genetic mutations in TRPV4 have been identified in various channelopathies including ∼20 skeletal and peripheral nervous system disorders in humans." (PMID 39909371, 2025). "Remarkably, most residues involved in polar TRPV4-RhoA interactions are subjects of disease-causing mutations in TRPV4-linked channelopathies, including peripheral neuropathy and skeletal dysplasia." (PMID 37353478, 2023). "The involvement of mechanosensitive ion channels in skeletal development has been highlighted by the effects of hereditary functional mutations (channelopathies) of transient receptor potential vanilloid 4 (TRPV4)." (PMID 36696489, 2023). "The precise mechanisms of TRPV4-related channelopathies remain poorly understood; however, in many disorders caused by TRPV4 mutations or non-genetic factors, an increased Ca2+ influx through the channel results in intracellular Ca2+ overload and subsequent cell degeneration or apoptosis." (PMID 39909371, 2025). "We further demonstrate that different point mutants of TRPV4 induce different mitochondrial morphology and have different levels of mitochondrial translocation, collectively suggesting that TRPV4-mutation-induced bone disorders and other channelopathies are mostly due to mitochondrial abnormalities." (PMID 37377733, 2023). "Diseases with defective bone development such as metatropic dysplasia, brachyolmia, spondylo-epiphyseal dysplasia of Kozlowski type, spondylo-epiphyseal dysplasia of Maroteaux type (pseudo-Morquio syndrome type 2) and parastremmatic dysplasia are also associated with TRPV4 channelopathies." (PMID 21420431, 2011). "The C-terminal tail also harbors a putative autoinhibitory domain (AID) that maintains the closed state of TRPV4 likely through electrostatic interactions, and disruption of these interactions leads to a gain of function (GOF) of TRPV4 and channelopathies." (PMID 39909371, 2025). "This suggests that TRPV4-mediated channelopathies affect mitochondrial structure-function-metabolism in a “case-by-case” manner and induce a “wide range of abnormalities” (i.e., mild to severe)." (PMID 37377733, 2023). "The functional impairment induced by TRPV4 antagonists cannot be directly compared to that of TRPV4 channelopathies." (PMID 36696489, 2023). "In that context, our data strongly suggest that TRPV4-mediated channelopathies mostly represent different forms of mitopathy." (PMID 37377733, 2023). "We recently extended the spectrum of TRPV4 channelopathies to another clinical entity, central giant cell lesion of the jaws (GCLJ), also known as giant cell granuloma." (PMID 33685999, 2022). "Pathogenic germline variants in Transient Receptor Potential Vanilloid 4 Cation Channel (TRPV4) lead to channelopathies, which are phenotypically diverse and heterogeneous disorders grossly divided in neuromuscular disorders and skeletal dysplasia." (PMID 33685999, 2022). "Here we report two unrelated women with a de novo germline p.Leu619Pro TRPV4 variant and an overlapping systemic disorder affecting all organs individually described in TRPV4 channelopathies." (PMID 33685999, 2022). "Our findings define a novel polysystemic syndrome due to germline TRPV4 p.Leu619Pro and further extend the spectrum of TRPV4 channelopathies." (PMID 33685999, 2022). "It is noticeable that TRPV4 channelopathies display a striking phenotypic variability, despite the disease-causing mutations being located in the same channel domains." (PMID 33467654, 2021).
channelopathies (continued). "Their findings extend the spectrum of TRPV4 channelopathies and provide rationale for targeted therapies at the bedside in GCLJ." (PMID 30385747, 2018). "Our data extend the spectrum of TRPV4 channelopathies and provide rationale for the use of TRPV4 and RAS/MAPK antagonists at the bedside in GCLJ." (PMID 30385747, 2018). "TRPV4 channelopathies are responsible for a number of hereditary sensory and motor neuropathies as well as diseases with defects in bone development." (PMID 21420431, 2011). "Previous studies have identified the importance of TRPV4 in cartilage and bone mechanotransduction and, separately, the involvement of TRPV4 channelopathy in skeletal malformations, yet its role in the regulation of skeletal development has not previously been investigated." (PMID 36696489, 2023). "This indicates a mechanism by which mechanical loading could direct morphogenesis during cartilage development and by which TRPV4 channelopathies may lead to joint malformations." (PMID 36696489, 2023). "Therefore, while the involvement of TRPV4 in skeletal development is evidenced by the impact of TRPV4 channelopathies on abnormal skeletal formation, this study demonstrates the specific mechanoregulatory involvement of TRPV4 in prenatal joint development." (PMID 36696489, 2023). "This overlapping genotype–phenotype relation suggests that the underlying pathogenic mechanisms of skeletal and nerve TRPV4 channelopathies are not always mutually exclusive." (PMID 33467654, 2021). "Notably, hereditary TRPV4 channelopathies are never associated with GCLJ and do not have mutations affecting the M713 residue which seem exclusive to this entity." (PMID 30385747, 2018). "Phosphorylation of TRPV4 by protein kinase A (PKA) and protein kinase C (PKC) is a predominant mechanism for channel regulation, especially in the cytoplasmic domains due to their importance in protein assembly, and channelopathies." (PMID 39909371, 2025). "Furthermore, our results were consistent with a summary of TRPV4 channelopathies reporting an increase in conductivity in V620I but no change in T89I." (PMID 36810131, 2023).
endometrial cancer (12 papers, 2020 to 2025). Primary or metastatic malignant neoplasm involving the endometrium (mucous membrane that lines the endometrial cavity). "Additionally, the receptor TRPV4 has been linked to metastasis in endometrial cancer via Rac1 and RhoA/ROCK signalling and there is an established link for TRPV4-Cdc42-N-WASP signalling in glioblastoma migration." (PMID 34196668, 2021). "The levels of free calcium and TRPV4 in the cancer cells of endometrial cancer FIGO stage II-IV were significantly higher than those in stage I (Déliot and Constantin, 2015)." (PMID 40655948, 2025). "TRPV4-mediated calcium influx modulates endometrial cancer cell migration, both in vitro and in vivo, via the activation of the RhoA/ROCK1 pathway, which in turn orchestrates cytoskeletal remodelling." (PMID 41226294, 2025). "Further investigation revealed the TRPV4 channel as a significant player in the etiopathogenesis of endometrial cancer." (PMID 41226294, 2025). "This study verified that TRPV4 is closely related to the occurrence and development of endometrial cancer both in vitro and in vivo." (PMID 40655948, 2025). "Previous study found that calcium ion and TRPV4 was required for calcium influx and contributes broadly to the development of endometrial cancer." (PMID 35816294, 2022). "TRPV4 has also been associated with Rho/ROCK pathway, cytoskeletal changes and invasion in cancer models: In endometrial cancer, TRPV4 promotes metastasis by Rho/ROCK-induced cytoskeletal changes." (PMID 34356643, 2021). "Furthermore, TRPV4 regulates the cytoskeleton of endometrial cancer cells through the RhoA/ROCK1 pathway, thereby promoting metastasis." (PMID 39895789, 2025). "Interestingly, TRPV4 exerts an impact on cell migration by regulating the actin cytoskeleton in gastric cancer, ovarian cancer, glioma cancer cells and endometrial cancer 9, 135-137." (PMID 35173539, 2022). "TRPV4 also promotes metastasis of endometrial cancer cells by regulating the RhoA/ROCK1 pathway." (PMID 34262942, 2021). "Additionally, in endometrial cancers, TRPV4 regulates cancer cell invasion through RhoA/ROCK1-dependent cytoskeletal changes and in glioma cancer cells TRPV4 promotes invasion through Akt/Rac1 signaling pathway." (PMID 34356643, 2021).
endothelial dysfunction (12 papers, 2015 to 2025). In vascular diseases, endothelial dysfunction is a systemic pathological state of the endothelium (the inner lining of blood vessels) and can be broadly defined as an imbalance between vasodilating and vasoconstricting substances produced by (or acting on) the endothelium. "Despite the established importance of TRPV4 channels in regulating vascular reactivity in previous literature, the specific role of TRPV4 and the underlying mechanisms in aging‐related endothelial dysfunction remain incompletely understood." (PMID 39744893, 2025). "We concluded that impaired TRPV4-mediated Ca2+ signaling causes endothelial dysfunction and that TRPV4 is a potential target for clinical treatment of age-related vascular system diseases." (PMID 26947561, 2016). "Because increasing the TRPV4 expression using gene delivery by lentiviral vectors restored the reduced TRPV4 agonist- and flow-induced vasorelaxations in aged rats, reduced expression of endothelial TRPV4 appears causally related to the age-associated endothelial dysfunction in this model." (PMID 34616307, 2021). "Taken together, these results indicate that blocking TRPV4 channels protects against the endothelial dysfunction caused by LPS, by reducing the pro-inflammatory and pro-coagulant state of the endothelium and largely preserving endothelial-dependent vasodilation and barrier function." (PMID 27653046, 2016). "Another notable aspect of the current study is the discovery of Thonningianin A and Carfilzomib as potential therapeutic agents for mitigating aging‐related endothelial dysfunction impaired vasodilation by restoring the interaction between TRPV4 and GPR35." (PMID 39744893, 2025). "Nevertheless, what should be noted here is that both studies highlight endothelial TRPV4 as a key factor contributing to the endothelial dysfunction in genetic hypertension." (PMID 34616307, 2021). "Since endothelial dysfunction in sepsis also confers increased vascular permeability, we tested the role of TRPV4 channels in this process by measuring hydraulic conductivity (Lp) in mesenteric arteries." (PMID 27653046, 2016). "In support of the development of endothelial dysfunction in sepsis, LPS injection reduced TRPV4 sparklets and IP3-mediated Ca2+ pulsars in Fluo-4–loaded en face mesenteric arteries." (PMID 27653046, 2016). "However, the role and mechanisms of TRPV4 in aging‐related endothelial dysfunction remain incompletely understood." (PMID 39744893, 2025). "However, the specific role of TRPV4 in aging‐related endothelial dysfunction warrants further elucidation." (PMID 39744893, 2025). "Subsequently, we revealed that intensive GPR35‐TRPV4 interaction significantly contributes to endothelial dysfunction during aging, utilizing TRPV4 endothelial‐specific knockout (TRPV4EC−/−), AAV‐FLT1‐shRNA (GPR35) mice, and GPR35 overexpressed/knocked‐down HUVECs." (PMID 39744893, 2025). "TRPV4 activation by β1-integrins might explain why high ECM stiffness, such as during inflammation or aging, causes endothelial dysfunction in a pathway that involves TRPV4-mediated Ca2+ signalling." (PMID 39696463, 2024). "Because endothelial dysfunction is a precursor to CVD, a better understanding of the mechanisms underlying impaired TRPV4 channels could lead to novel therapeutic strategies for CVD prevention." (PMID 34616307, 2021). "Moreover, increasing evidence reveals that endothelial TRPV4 are involved in the pathophysiological process of endothelial dysfunction in certain vascular beds in cardiometabolic disease conditions." (PMID 34616307, 2021). "Despite the provocative association of TRPV4 function with certain key features of sepsis, including systemic inflammatory responses, endothelial dysfunction and subsequent hypotension and edema formation, whether activation of TRPV4 channels is involved in the development of sepsis is unknown." (PMID 27653046, 2016).
endothelial dysfunction (continued). "The diminished function of endothelial TRPV4, rather than changes in its expression, plays a significant role in aging‐related endothelial dysfunction." (PMID 39744893, 2025). "Other drugs that could limit chemotaxis and endothelial dysfunction are blockers of RAGE and transient receptor potential vanilloid 4 (TRPV4) channel inhibitors." (PMID 34000622, 2021). "Moreover, it will be important to define the mechanisms by which hyperglycemia alters TRPV4 and SK channel expression, distribution and interaction, and whether TRPV4 and SK channel function are actually altered in native endothelial cells leading to endothelial dysfunction." (PMID 32594191, 2021).
Hydrocephalus (12 papers, 2016 to 2025). Hydrocephalus is an active distension of the ventricular system of the brain resulting from inadequate passage of CSF from its point of production within the cerebral ventricles to its point of absorption into the systemic circulation. "TRPV4 can be activated chemically via inflammatory mediators (arachidonic acid metabolites or cytokines) or physically via mechanical (pressure) and osmotic changes - mechanisms also known to cause hydrocephalus." (PMID 39364470, 2024). "To resolve the molecular link between LPA and brain water accumulation, we determined the ability of LPA to act as an agonist of the ion channel TRPV4, the activity of which is modulated by lipids and which may be implicated in hydrocephalus formation." (PMID 36068581, 2022). "TRPV4 has been implicated in CSF secretion following demonstration of its ability to modulate transepithelial ion flux in choroid plexus cell lines and of TRPV4 antagonists effectively alleviating ventriculomegaly in a genetic animal model of hydrocephalus." (PMID 36068581, 2022). "In adult rats, LPA acts directly on TRPV4 channels, leading to overactivation of NKCC1, promoting excessive CSF secretion, and consequently causing hydrocephalus." (PMID 39908266, 2025). "Their data supported the relationship between TRPV4 and hydrocephalus development from cell surface expression or activation changes." (PMID 39364470, 2024). "A study utilizing a genetic rat model of communicating hydrocephalus showed that two different TRPV4 antagonists inhibited ventriculomegaly development." (PMID 39364470, 2024). "Through the role of TRPV4 in regulating transepithelial ion flux and cell permeability in the choroid plexus, there is the possible utility of TRPV4 antagonists for most forms of hydrocephalus." (PMID 39364470, 2024). "Two of these channels, the non-specific cation channel, transient receptor potential vanilloid 4 (TRPV4) and the sodium, potassium, 2 chloride channel 1 (NKCC1), have recently been implicated in the pathophysiology of hydrocephalus." (PMID 37596666, 2023). "In a genetic rat model of hydrocephalus, the Tmem67 model, treatment with TRPV4 antagonists ameliorated hydrocephalic development." (PMID 37047646, 2023). "The promising safety and tolerability data on TRPV4 antagonists in general, suggest that additional preclinical mechanistic studies examining the role for TRPV4 in the pathophysiology of hydrocephalus are crucial." (PMID 36050779, 2022). "Inhibition of TRPV4 modulates transepithelial ion flux in immortalized choroid plexus cell lines and abolishes ventriculomegaly in a genetic rat model of hydrocephalus." (PMID 36068581, 2022). "We suspected that TRPV4 antagonism would also result in reduced CSF secretion due to its success in ameliorating symptoms of CSF accumulation in hydrocephalus." (PMID 34573139, 2021). "Further, a recent preclinical study found that chronic TRPV4 antagonism effectively ameliorates symptoms of hydrocephalus (cranial expansion and ventriculomegaly) in a genetic model of the disease." (PMID 34573139, 2021). "Tmem67–/– rats develop hydrocephalus that is ameliorated by treatment with 2 different TRPV4 antagonists." (PMID 32938829, 2020). "TRPV4 agonist treatment exacerbated the hydrocephalus in the affected animals, although this effect was only statistically significant when comparing the agonist-treated versus vehicle-treated homozygous pups in the horizontal head dimension." (PMID 32938829, 2020). "Our goal is to provide a preclinical basis for consideration of TRPV4 as a potential drug target in the treatment of hydrocephalus, and the efficacy of TRPV4 antagonists in a genetic model of the disease represents an initial step toward that goal." (PMID 32938829, 2020). "Conversely, treatment with the TRPV4 antagonist HC067047 ameliorated the hydrocephalus as measured by either cranial dimensions." (PMID 32938829, 2020).